OR6C3 (olfactory receptor family 6 subfamily C member 3)
Description:
Odorant receptor.
Synonyms: OST709
Tractability: Antibody: UniProt places it where antibodies can reach, with medium confidence; UniProt predicts a signal peptide or a membrane-spanning region; its Gene Ontology location is reachable by antibodies, with medium confidence.
Gene: Protein-coding gene on chromosome 12 (55,330,043 to 55,332,687, forward strand). Ensembl gene ENSG00000205329.
Subcellular location: Cell membrane
Pathways (Reactome):
Sensory Perception: Expression and translocation of olfactory receptors
Gene Ontology:
Molecular function: olfactory receptor activity; G protein-coupled receptor activity
Biological process: sensory perception of smell; detection of chemical stimulus involved in sensory perception of smell; G protein-coupled receptor signaling pathway
Cellular component: membrane; plasma membrane
Genetic constraint (gnomAD): Loss-of-function variants: 1 observed, 0.27 expected, observed/expected ratio (o/e) 3.72. That is too few expected variants to judge how well the gene tolerates losing a copy. Missense variants: 485 observed, 378.73 expected, observed/expected ratio (o/e) 1.28, 90% interval 1.19 to 1.38. Synonymous variants: 177 observed, 144.95 expected, observed/expected ratio (o/e) 1.22, 90% interval 1.08 to 1.38.
Homologues: Orthologues: dog OR6C3I (94% identical), rabbit OR6C3 (93% identical), dog OR6C3I (90% identical), guinea pig OR6C3 (89% identical), rat Or6c3 (89% identical), rat Or6c3d (89% identical), mouse Or6c3 (88% identical). Paralogues in human: OR6C1 (74% identical), OR6C75 (72% identical), OR6C76 (72% identical), OR6C74 (68% identical), OR6C70 (68% identical), OR6C4 (66% identical), OR6C6 (66% identical), OR6C2 (65% identical), OR2AP1 (64% identical), OR6C65 (64% identical), OR6C68 (59% identical), OR6T1 (46% identical), and 6 more.